IL1B (interleukin 1 beta)
Diseases named in the same sentence as IL1B in open-access papers (continued):
Sharing a sentence is not in itself a finding about the gene and the disease.
atherosclerosis (continued). "For example, low-dose methotrexate used in cardiovascular inflammatory reduction trial (CIRT) did not lower IL-1β, IL-6, CRP levels, or reduce cardiovascular events in patients with stable atherosclerosis." (PMID 36555898, 2022). "According to other reports IL-1β and NLRP3 are not involved in atherosclerosis development, while IL-1α has a key role." (PMID 32545788, 2020). "Interestingly, even though TLR4 deficiency reduced atherosclerosis extent, the lack of MyD88, an adaptor protein in the TLR signaling cascade, further reduced it, possibly because it participates in the signal-transduction pathway of the receptors for IL-1β and IL-18." (PMID 30558209, 2018). "In addition, the serum TNF-α and IL-1β levels were increased in atherosclerosis rabbits, and kaempferol groups showed lower TNF-α and IL-1β levels, indicating that the down-regulation of E-sel, ICAM-1, VCAM-1 and MCP-1 might be mediated by the reducing of TNF-α and IL-1β." (PMID 23895132, 2013).
diabetes (936 papers, 2006 to 2026). "In diabetic conditions, MGO causes elevated levels of IL-6 and other cytokines such as IL-1β and therefore inflammation in patients, contributing to the pathology of diabetes." (PMID 41000474, 2025). "Pro-inflammatory cytokines, like interleukin-1 beta and interferon gamma, are known to activate signalling pathways causing pancreatic beta cell death and dysfunction, contributing to the onset of diabetes." (PMID 39774736, 2025). "Sitagliptin effect on diabetes-associated inflammation was assessed by measuring cardiac levels of IL-1β, TNF-α, and CRP, which were significantly elevated (p ≤ 0.001) in diabetic rats." (PMID 40867548, 2025). "Diabetes is associated with persistent low-grade inflammation, characterized by elevated levels of proinflammatory cytokines such as IL-1β, IL-6, and TNF-α." (PMID 41438123, 2025). "Ceramides, particularly, have been associated with the inflammatory response in diabetes where they trigger Caspase‐1 activation and IL‐1β secretion impairing insulin sensitivity." (PMID 39327931, 2025). "In a rodent model of diabetes, rats with 6 weeks of glucose fluctuation had higher mRNA expression of IL-1β, TNF-α, and abnormal expression of apoptosis-associated genes in the hippocampus." (PMID 40445939, 2025). "To test this mechanism in humans, we exposed isolated pancreatic islets from human donors to the diabetes-associated proinflammatory cytokines IL-1β and IFNγ, and evaluated the effects of fenofibrate on beta cell function and death." (PMID 39477880, 2025). "This study aims to investigate the functional role of IL-1β protein levels and the IL-1β (rs16944) gene polymorphism in patients with diabetes mellitus." (PMID 41137275, 2025). "We explore the physiological role of the IL-1β pathway in insulin secretion and the relationship between circulating levels of IL-1β and the development of diabetes and associated diseases." (PMID 39496966, 2025). "IL-1β and IL-18 are closely related to the occurrence and development of diabetes mellitus and are associated with metabolic homeostasis, inflammation, and IR." (PMID 41264598, 2025). "We examined levels of key factors that are associated with proinflammation and significantly altered in diabetes (IL1β, IL6 and IL10) and that are associated with angiogenesis (VEGF-A) in M1 macrophages." (PMID 38270651, 2024). "Diabetes mellitus–associated atrial fibrillation is caused by macrophage IL-1β through mitoROS modulation of RyR2 Ca2+ leak." (PMID 38889387, 2024). "The compensated IL1β activation in diabetes perhaps caused incompleteness of adequate immune reaction." (PMID 38270651, 2024). "The only significant difference observed at the baseline assessment between the groups was that patients in married had lower levels of IL-1β (P = 0.01), and diabetes was associated with lower levels of TNF-α (P = 0.04)." (PMID 38459460, 2024). "Married status was associated with lower levels of IL-1β, and diabetes was associated with lower levels of TNF-α." (PMID 38459460, 2024). "The STZ-induced diabetes presented in this study was associated with increased IL-1β levels, contributing to inflammation and β-cell destruction." (PMID 39337082, 2024). "The IL1B rs1143634 variant was associated with lower calculus removal necessity in type 1 diabetes mellitus patients (p = 0.030)." (PMID 38248068, 2024). "Intriguingly, there was a dichotomy in the association of WAT IL-1β-secretion to diabetes risk factors depending on the apoB-group and WAT stimulus." (PMID 37914804, 2023). "As noted in Section 1.4, the tooth loss genotype, IL1A-889(A)+IL1B+3954(T) occurs at a frequency of 68% in hosts presenting with at least two of three periodontitis risk factors, smoking, diabetes, or teeth cleaned professionally twice or less per year." (PMID 37762554, 2023). "Several studies have linked the deleterious effects of IL-1β with different pathological conditions, such as diabetes, AD, and AMD." (PMID 37110558, 2023).
diabetes (continued). "The results showed that the expression levels of NLRP3, caspase 1, IL-1β and IL-18 were increased in CD38flox mice with diabetes compared with the normal group, whereas CD38 deficiency significantly decreased the expression of these genes at the mRNA level." (PMID 37958991, 2023). "While IL-1β was previously linked with the risk of diabetes, evidence for increased IL-1β levels is limited due to the typically low circulating levels of IL-1β." (PMID 37710315, 2023). "In this study, we found that diabetes-induced vascular endothelial dysfunction was associated with increased levels of inflammatory cytokines, such as IL-1β and IL-18, which were mediated by the FTO-TNIP1-NF-κB network." (PMID 37781923, 2023). "In individuals with diabetes, immunodeficient conditions, or undergoing biological treatments, abnormal cytokine networks or ROS production can lead to excessive levels of IL-1β in the tissue and cause the formation of neutrophilic caseous granulomas." (PMID 36674717, 2023). "Another drug, Glyburide, has been shown to produce potentially adverse side effects on neutrophil and monocyte-mediated immune responses against Mtb (reducing IL-1β and IL-8 production) thereby exacerbating susceptibility of diabetes patients to Mtb infection." (PMID 38032920, 2023). "Adjusting for WAT NLRP3 and IL1B mRNA and mostly for maximal LPS/ATP-induced IL-1β-secretion attenuated the association of plasma apoB with diabetes risk factors." (PMID 37914804, 2023). "The ameliorative effect of ST on diabetes-associated inflammation was explored via the determination of hepatic IL-1β, IL-18, and TNF-α levels." (PMID 38131990, 2023). "The levels of proinflammatory cytokines (IL-1β) are exceptionally high in conditions of diabetes-associated complications." (PMID 35795278, 2022). "Other findings included a chronic low-grade inflammation in diabetes patients with decreased glucose tolerance, which was caused in part by IL-1β generated by glucose and further hindered insulin secretion." (PMID 35337139, 2022). "IL-17A knockout reduces the levels of TNF-a, IFN-c and IL-1b in Akita mice, suggesting that IL-17A is strongly associated with proinflammatory cytokine-driven inflammatory responses in diabetes progression." (PMID 36582230, 2022). "Emerging evidence has showed that numerous cytokines, including TGFβ, IL-6, IL-1β, and IL-21, are associated with bone remodeling in diabetes." (PMID 35993048, 2022). "ChREBP was also associated with up-regulation of several cytokines (TNF-α, IL-1β, and IL-6) in patients with type 2 diabetes mellitus, promoting the inflammatory responses and apoptosis of mesangial cells." (PMID 36741695, 2022). "Diabetes is characterized by the presence of increased proinflammatory cytokines, being IL-1β one of the main inflammatory markers associated in the reduction of insulin signaling leading to insulin resistance in GDM." (PMID 35303833, 2022). "IPA also predicted activation of TNF-α, IL-6, and IL-1β cellular signaling pathways, where these key immunoregulators are known to be associated with diabetes-induced metabolic inflammation." (PMID 35304484, 2022). "IL-1β is an important multifunctional cytokine, which is closely related to the cause and process of periodontitis and diabetes." (PMID 36430410, 2022). "Interleukin-1β (IL-1β) is one of the most potent molecules of the innate immune system implicated in macro- and micro-vascular complications of diabetes." (PMID 32471207, 2020). "As diabetes progresses, increased IL1β expression was linked to insulin resistance and beta cell destruction; with damaged beta cells eventually failing to respond to increasing insulin demand, due their rapid death and functional impairment." (PMID 33182622, 2020). "More importantly, drug inhibition of IL-1β or gene knockout of the receptor for IL-1β significantly prevented the degeneration of retinal capillaries caused by diabetes." (PMID 32019593, 2020).
diabetes (continued). "On the other hand, the diabetes-induced expression of proinflammatory cytokines such as Tnf-α, Il-1β, and Il-6 was substantially diminished by Pdk2-deficiency." (PMID 33219201, 2020). "TNF-α and IL-1β play a pathogenic role in DR since they contribute to diabetes-induced degeneration of retinal capillaries." (PMID 31921199, 2019). "NLRP3 inflammasome-caused IL-1β expression has been found positively associated with the development of bisphosphonate-related osteonecrosis in diabetes." (PMID 31146750, 2019). "Prolonged exposure to pro-inflammatory cytokines, particularly the combination of IL-1β and TNFα, induced pancreatic beta cell apoptosis, which is one of the major causes of islet inflammation during the development of diabetes." (PMID 31728004, 2019). "IL-1β, a potent inflammatory cytokine associated with islet failure in both types of human diabetes, served as a positive control." (PMID 31781116, 2019). "Previous studies have implicated high IL-1β as being associated with the inflammatory pathophysiology of stroke, diabetes and cardiovascular diseases." (PMID 30206230, 2018). "Considering the role of proinflammatory cytokines on the pathogenesis of diabetes, population with detectable levels of circulating IL-1β cytokines have increased risk to develop diabetes." (PMID 30410469, 2018). "We indicate that High GCF IL-1β is associated with prevalent diabetes and thick carotid intimal-medial wall thickness (IMT)." (PMID 30206230, 2018). "Being critical mediator of β-cell death in type 1 diabetes, NF-κB/IL-1β signaling pathway was implicated in β-cell death in both types of diabetes." (PMID 30024959, 2018). "Pathological NLRP3 inflammasome signaling and IL-1β processing has been implicated in widespread conditions beyond diabetes and heart disease, such as gout, cancer and Alzheimer's disease." (PMID 29515457, 2018). "Hyperglycemia and oxidative stress associated with diabetes sustain prolonged influx of inflammatory cells through inducing excessive proinflammatory cytokines (IL-1β, TNF-α, etc.)production." (PMID 28542422, 2017). "Excessive IL-1β production is closely linked to chronic inflammatory disease, including diabetes, atherosclerosis, and gout." (PMID 28164132, 2017). "IL-1β is known to cause both pancreatic β cells impairment and destruction during the type 1 diabetes mellitus development." (PMID 28985731, 2017). "Elevated levels of TNF-α in the liver are associated with the severity of diabetes, and IL-1β adversely affects the insulin signaling pathway and contributes to insulin resistance." (PMID 27929393, 2016). "Lastly, the robustness of hubs was determined by challenging islets with cytokine cocktails (IL-1β/IL-6 or IL-1β/TNF-α) to re-create the pro-inflammatory milieu thought to be associated with diabetes." (PMID 27452146, 2016). "Inflammatory cytokines such as TNF-α, IL-6, and IL-1β can cause adipocyte dysfunction, which is involved in the development of diabetes." (PMID 27878229, 2016). "Interleukin-1β (IL-1β) has been implicated as a key proinflammatory cytokine involved in the pancreatic islet inflammation of type 2 diabetes mellitus (T2DM)." (PMID 27152706, 2016). "Inflammation, and in particular IL-1β, has been implicated in the pathogenesis of beta cell dysfunction in type 2 diabetes mellitus." (PMID 27421726, 2016). "Results from these studies aroused our interests to implement further investigation on the association between IL-1β and cardiovascular complications of diabetes, DCM especially." (PMID 26394923, 2015). "Increased production of IL-1β has been linked to a pro-inflammatory environment in the pancreatic islets that leads to beta-cell dysfunction and death in type 2 diabetes mellitus." (PMID 25518980, 2014). "Inflammatory cytokines, such as interleukin 1 beta (IL1B), have a key regulatory role in the atherosclerotic process and are also implicated in the failure of β-cells during diabetes development." (PMID 24086293, 2013).
diabetes (continued). "Interleukin-1beta (IL-1β) is a major cause for induction of various inflammatory mechanisms that are decisively involved to provoke pathogenesis of type 2 diabetes mellitus (T2DM)." (PMID 23409091, 2013). "IL-1β is a proinflammatory cytokine that is implicated in the pathogenesis of many inflammatory diseases including diabetes, rheumatoid arthritis and genetic auto-inflammatory disorders." (PMID 23483669, 2013). "The diabetes-induced impairments in IL-1β signaling were linked to aberrant mitochondrial bioenergetics." (PMID 24152426, 2013). "The activation of transcription factor NF-κB induced by both TNF-α and IL-1β was associated with the pathogenesis of diabetes mellitus." (PMID 22922276, 2012). "It has been demonstrated that IL-1β-mediated inflammation is augmented in db/db mice due to diabetes-associated loss of IL-1β counter-regulation." (PMID 22953001, 2012). "Inhibition of IKKβ activity prevents diet-induced diabetes in P. obesus and inhibits IL-1β induced reactive oxygen species, loss of insulin production and beta cell death in vitro." (PMID 20948968, 2010). "Patients with elevated levels of IL-6 and IL-1β have a higher risk of even developing diabetes." (PMID 41000474, 2025). "Furthermore, mature adipocyte lactate is associated with metabolic disorders such as diabetes, and it has been demonstrated to elevate the level of IL-1β in macrophages and promote adipose tissue inflammation." (PMID 40919599, 2025). "The objective of this study was to examine whether, among individuals with phenylketonuria and type 1 diabetes mellitus, those with the IL1B rs1143634 and/or DEFB1 rs11362 genetic variants exhibit a higher periodontitis risk compared to healthy controls." (PMID 38248068, 2024). "In several inflammatory contexts, including diabetic nephropathy, miR-146a displayed an anti-inflammatory effect, since miR-146a deficiency during diabetes led to increased expression of M1 activation markers and proinflammatory cytokines (IL1β, IL18) and suppression of M2 markers in macrophages." (PMID 37071788, 2023). "Development of new drugs targeting the NLRP3 inflammasome, IL-1 receptor antagonists, agents that can remove IL-1β from the circulation, etc., may reduce the susceptibility of diabetics to air pollution." (PMID 37919797, 2023). "Studies have shown that the release of HMGB1 may cause necrosis in islet β cells induced by IL-1β and may lead to diabetes onset." (PMID 37065747, 2023). "To explore whether the WAT NLRP3 inflammasome/IL-1β pathway is related to higher diabetes risk factors in subjects with high-apoB, we used partial correlation analysis." (PMID 37914804, 2023). "Inflammatory factors such as TNF-α and IL-1β cause β-cell injury and dysfunction in diabetes." (PMID 37817130, 2023). "Given that interleukin (IL)-1β is a central driver of the cardiovascular complications caused by diabetes and is an established target for clincal intervention, we also examined the relative expression of IL-1β and found it to be enhanced in cardiac tissue of mice fed an HFHS diet." (PMID 36383638, 2023). "Correspondingly, certain variants (alleles) of genes that encode a genotype consisting of Interleukins 1A and 1B (IL1A and IL1B) were found to detect individuals (hosts) with tooth loss due to severe periodontitis after adjusting for smoking, diabetes and professional dental care." (PMID 37762554, 2023). "It is already described that patients can establish a chronic inflammation state under diabetic conditions, characterized by a decompensated secretion of pro-inflammatory cytokines, such as TNF-α, IL-1β and IL-6, and it is suggested as the major cause of comorbidities related to diabetes." (PMID 37122742, 2023). "Notably, the contradictory associations of WAT IL-1β-secretion with diabetes risk factors in the low-apoB and high-apoB groups cancelled each other when all subjects were combined." (PMID 37914804, 2023).